XCR1 (X-C motif chemokine receptor 1)
Description:
Receptor for chemokines SCYC1 and SCYC2. Subsequently transduces a signal by increasing the intracellular calcium ions level. Receptor for XCL1/Lymphotactin.
Synonyms: CCXCR1; GPR5
Tractability: Small molecule: it belongs to a druggable protein family. Antibody: its Gene Ontology location is reachable by antibodies, with high confidence; UniProt places it where antibodies can reach, with medium confidence; UniProt predicts a signal peptide or a membrane-spanning region.
Target class: Chemokine receptor; Membrane receptor; Peptide receptor (family A GPCR); XC chemokine receptor; Family A G protein-coupled receptor
Gene: Protein-coding gene on chromosome 3 (46,016,990 to 46,085,825, reverse strand). Ensembl gene ENSG00000173578.
Subcellular location: Cell membrane
Pathways (Reactome):
Signal Transduction: Chemokine receptors bind chemokines; G alpha (q) signalling events
Gene Ontology:
Molecular function: protein binding; C-C chemokine binding; C-C chemokine receptor activity; chemokine receptor activity; G protein-coupled receptor activity
Biological process: calcium-mediated signaling; cell chemotaxis; chemotaxis; G protein-coupled receptor signaling pathway; G protein-coupled receptor signaling pathway, coupled to cyclic nucleotide second messenger; immune response; inflammatory response; positive regulation of cytosolic calcium ion concentration; chemokine-mediated signaling pathway
Cellular component: external side of plasma membrane; plasma membrane; membrane
Genetic constraint (gnomAD): Loss-of-function variants: 0 observed, 0.98 expected, observed/expected ratio (o/e) 0, 90% interval 0 to 1.73. That is too few expected variants to judge how well the gene tolerates losing a copy. Missense variants: 356 observed, 445.85 expected, observed/expected ratio (o/e) 0.8, 90% interval 0.73 to 0.87. Synonymous variants: 187 observed, 198.86 expected, observed/expected ratio (o/e) 0.94, 90% interval 0.83 to 1.06.
Homologues: Orthologues: chimpanzee XCR1 (99% identical), macaque XCR1 (96% identical), pig XCR1 (78% identical), dog XCR1 (77% identical), rabbit XCR1 (77% identical), guinea pig XCR1 (73% identical), mouse Xcr1 (69% identical), rat Xcr1 (68% identical), tropical clawed frog ccr2 (43% identical), zebrafish xcr1b.1 (39% identical), zebrafish xcr1a.1 (37% identical). Paralogues in human: ACKR2 (35% identical), CCR1 (34% identical), CCR4 (33% identical), CCR8 (32% identical), CCR2 (32% identical), CCR3 (31% identical), CCR5 (31% identical), CX3CR1 (31% identical), CXCR2 (30% identical), CXCR1 (29% identical), CXCR3 (29% identical), CXCR4 (29% identical), and 11 more.
Diseases named in the same sentence as XCR1 in open-access papers:
XCR1 is named in the same sentence as 110 diseases in open-access papers, as found by Europe PMC text mining. Sharing a sentence is not in itself a finding about the gene and the disease. The quoted sentences say what the papers report.
COVID-19 (30 papers, 2020 to 2026). A disease caused by infection with severe acute respiratory syndrome coronavirus 2. "In our study, XCR1 variants were associated with severe COVID-19, which has also been confirmed in other studies." (PMID 37547597, 2023). "Strikingly, the Severe Covid-19 GWAS Group (2020) detected a small genomic region containing six genes that significantly associate with severe COVID-19, one of which is XCR1." (PMID 34616619, 2021). "XCR1 is in a small genomic region that is implicated in severe COVID-19 by genome-wide association studies (Severe Covid-19 GWAS Group, 2020; Fricke-Galindo & Falfán-Valencia, 2021)." (PMID 34616619, 2021). "Also, recently, it was found that a region of our DNA situated on chromosome 3 (locus 3p21.31), spanning a length of 49.3 kb, consisting of 6 genes (SLC6A20, LZTFL1, CCR9, FYCO1, CXCR6, and XCR1), was associated with the risk of developing severe COVID-19." (PMID 37929242, 2023). "Additionally three genes (CCR1, FYCO1, and XCR1) were not only associated with COVID-19, but also at least two cardiac traits." (PMID 36187959, 2022). "Notably, decreased genetically determined XCR1 in esophagus mucosa was also associated with a higher risk for severe COVID-19, indicating a potential pleiotropic effect of the gene." (PMID 35318325, 2022). "Furthermore, XCR1 maps to a region implicated in severe COVID-19 by a genome-wide association study (Severe Covid-19 GWAS Group, 2020)." (PMID 34616619, 2021). "We did not observe changes in the expression of any of the six genes clustered in the locus associated with respiratory failure in patients with COVID-19 (CCR9, SLC6A20, LZTFL1, CXCR6, XCR1, FYCO1)." (PMID 40722786, 2025). "A severe COVID-19 GWAS Group has identified genetic variants linked to genes such as SLC6A20, LZTFL1, CCR9, FYCO1, CXCR6, and XCR1 in patients experiencing respiratory failure due to COVID-19." (PMID 40143318, 2025). "A gene-based association test revealed a significant association in BAZ2B and in previously known COVID-19 risk loci: LZTFL1, XCR1, FYCO1, CCR9, and IFNAR2." (PMID 39361370, 2024). "The first and most significant locus described in GWAS associated with COVID-19 critical is 3p21.31, which encompasses six genes (SLC6A20, LZTFL1, CCR9, FYCO1, CXCR6, and XCR1) (The Severe COVID-19 GWAS Group, 2020)." (PMID 38226654, 2024). "We found six genes at locus 3p21.31 significantly associated with severe COVID-19: LZTFL1, FYCO1, XCR1, CCR9, TMLHE-AS1, and SCYL2." (PMID 37547597, 2023). "We found significant associations between COVID-19 and LZTFL1, FYCO1, XCR1, CCR9, TMLHE-AS1, and SCYL2 at 3p21.31." (PMID 37547597, 2023). "The first COVID-19 genome-wide association study identified the 3p21.31 gene cluster, including “SLC6A20, LZTFL1, CCR9, FYCO1, CXCR6, and XCR1” as a genetic susceptibility locus in severe patients with COVID-19 and respiratory failure." (PMID 37521836, 2022). "This study aimed to associate genetic variants in the SLC6A20, LZTFL1, CCR9, FYCO1, CXCR6, XCR1, and ABO genes with the risk of severe forms of COVID-19 in Amazonian Native Americans, and to compare the frequencies with continental populations." (PMID 35455670, 2022). "Our finding that XCR1 is ACE2’s 2nd highest ERC interactor lends independent support for a relationship between COVID-19 and XCR1." (PMID 34616619, 2021). "In conclusion, we detected three rare and four ultrarare variants in four COVID-19-related genes, SLC6A20, LZTFL1, XCR1 and FURIN, that are present only in the Brazilian dataset and predicted to affect protein function." (PMID 33824725, 2021). "TNFSF15 is a third immune response protein in the XCR1 RR subnetwork that shows elevated expression in patients with severe COVID-19." (PMID 34616619, 2021).
COVID-19 (continued). "Another study found that the genetic predisposition to colorectal or lung cancer was causally associated with a decreased or increased susceptibility to COVID-19 severity, respectively, and this association pointed to the LZTFL1, CCR9, FYCO1, CXCR6, XCR1, and ABO genes." (PMID 41375068, 2025). "In a study correlating gene and protein expression of 17 COVID-19 susceptibility genes with lung cancer prognosis, it was found that the hyperexpression of FYCO1, CXCR6, XCR1, and TAC4 in cancer cells was protective, whereas that of TMEM65 and OAS1 was a risk factor for SARS-CoV2 infection." (PMID 41375068, 2025). "The present study investigated genetic variants in the SLC6A20, LZTFL1, CCR9, FYCO1, CXCR6, XCR1, and ABO genes that are potentially related to severe forms of COVID-19 in Amazonian Native American populations, and compared their frequencies with continental populations." (PMID 35455670, 2022). "Instead, their protein evolutionary correlations suggest that ACE2 may play a contributory role to COVID-19, possibly through XCR1-related pathways, as suggested by the network analysis." (PMID 34616619, 2021). "Two loci associated with respiratory failure in COVID-19 were found, one of which was the GA-G insertion-deletion variant in locus 3p21.31 that is composed of six genes (SLC6A20, LZTFL1, CCR9, FYCO1, CXCR6, and XCR1)." (PMID 33791232, 2021). "The first GWAS analysis with 1980 patients with COVID-19 identified two loci associated with the most severe forms of COVID-19: one locus was 3p21.31, which includes the genes SLC6A20, LZTFL1, CCR9, FYCO1, CXCR6, and XCR1, while the other was 9q34.21, including the ABO blood group." (PMID 35455670, 2022). "Furthermore, it suggests that an interaction between ACE2 and XCR1 could be involved in COVID-19 pathologies." (PMID 34616619, 2021). "Through COVID-19-relevant transcriptome and enrichment gene sets, seven druggable targets with COVID-19-relevant functions were identified, including CCR9, CXCR6, XCR1, IL10RB, OAS1, OAS2, and OAS3." (PMID 37886583, 2023). "The high ERC between ACE2 and XCR1 and high reciprocal ranks of XCR1 to ICOS suggests that the disruption of an ACE2-XCR1 interaction could have a contributory role in COVID-19." (PMID 34616619, 2021). "Finally, two GWAS have identified the loci 3p21.31 (LZTFL1, SLC6A20, CCR9, FYCO1, CXCR6, and XCR1) and 9q34.2 (ABO) with COVID-19 severity." (PMID 33868239, 2021). "While the specific mechanism by which XCR1 might play a role in severe COVID-19 is not yet known, ERC results indicate its role may be mediated by ACE2 with XCR1’s ERCs also possibly indicating a broader functional role in coagulation." (PMID 34616619, 2021).
viral infection (9 papers, 2020 to 2025). "Our spatial analysis revealed that clustering P14 T cells preferentially interacted with XCR1+ DCs early during virus infection in the spleen, whereas interactions with LCMV-infected cells involved non-clustering T cells." (PMID 39994207, 2025). "Both wild-type and Δvxcl1 mutant virus infection led to a strong reduction in XCR1 surface expression." (PMID 38077365, 2023). "We found that immature chicken XCR1+ cDCs express a range of genes that potentially limit viral infection." (PMID 37954617, 2023). "Reductions in XCR1+ cDC1 and CLEC10A+ cDC2 may have functional implications for susceptibility to viral infections and tumor surveillance in CLL." (PMID 39399662, 2024). "These include genes encoding for WDFY4, which is essential for cross-presentation of cell-associated antigens by cDC1 via the cytosolic pathway and PPT1, which protects XCR1+ cDCs from viral infection by promoting antigen degradation and endosomal acidification." (PMID 37954617, 2023). "We also observed a population of naïve CD4 T cells (denoted ‘Xcl1+ naïve’) expressing Lef1 and Sell genes along with Xcl1, which is a ligand of XCR1 (or G protein-coupled receptor 5, GPR5), with increased expression on NK and CD8+ T cells during virus infection." (PMID 40096073, 2025). "Upon viral infection, activated CD8 T cells are known to recruit XCR1+ DC by producing XCR1+ DC." (PMID 35693801, 2022). "However, the number of proliferating T cells detected in the XCR1‐DTA mice was lower compared to the WT, suggesting that, as in the case of viral infections, despite the fact that type 2 DCs can prime CD8 T cells, type 1 DCs are still required for optimal T cell proliferation." (PMID 39382167, 2024).
colitis (8 papers, 2016 to 2024). Inflammation of the colon. "Consistent with the regulatory roles of intestinal T cells, XCR1+ DC-deficient mice showed exaggerated manifestations during chemically-induced colitis." (PMID 27005831, 2016). "Indeed, mice with XCR1-deficient cDC1 lack intraepithelial and LP T cell populations and are remarkably more susceptible to chemically-induced colitis." (PMID 36189323, 2022). "cDC1 deficiency in XCR1-DTA mice, or depletion of cDC1 by administration of diphtheria toxin to CLEC9A-DTR mice, leads to enhanced susceptibility to DSS-induced colitis." (PMID 36189323, 2022). "Exacerbation of colitis in XCR1-DTA mice, with their profoundly diminished intestinal T cell populations, is consistent with these reports." (PMID 27005831, 2016). "XCR1+ cDC1s are important for intestinal homeostasis and in particular the expression of XCR1; mice lacking XCR1 in cDC1 lack intraepithelial and lamina propria T cell populations, and are more vulnerable to chemically-induced colitis." (PMID 36675038, 2023). "In contrast to the absence of pathology in the steady-state, we found that the defects induced by the absence of XCR1+ DCs rendered XCR1-DTA mice significantly more susceptible to induced colitis compared with control mice." (PMID 27005831, 2016). "We showed that mice lacking XCR1+ DCs are specifically deficient in intraepithelial and lamina propria (LP) T cell populations, with remaining T cells exhibiting an atypical phenotype and being prone to death, and are also more susceptible to chemically-induced colitis." (PMID 27005831, 2016). "Mice lacking PD-L1+ and XCR1+ DC have a proinflammatory gut milieu associated with an increase in Th1/Th17 cells and a decrease in Treg cells and have exacerbated disease in the models of 5-FU-induced mucositis and DSS-induced colitis." (PMID 34389726, 2021). "Mice lacking programmed death 1 (PD-1)-L1+ or XCR1+ DCs exhibit a pro-inflammatory gut milieu associated with an increase in Th1/Th17 cells and a decrease in Treg cells in the models of 5-FU-induced mucositis and dextran sodium sulfate (DSS)-induced colitis." (PMID 34389726, 2021). "Similarly, specific depletion of XCR1+ CD103+ CD11b− cDC1 but not CD103+ CD11b+ cDC2 aggravated colitis in a low dose DSS model." (PMID 29570694, 2018). "In the absence of XCR1+ DCs, mice had increased colonic inflammation in the DSS-colitis model." (PMID 34389726, 2021).
breast carcinoma (7 papers, 2019 to 2025). "Further analysis in the breast cancer tissue microarrays revealed a positive correlation of cDC1 (XCR1+DCs) with XCL1-producing γδ T cells." (PMID 39209451, 2024). "Meanwhile, the XCL1/XCR1 axis also contributes to the progression of various diseases, including rheumatoid arthritis, breast cancer, and non‐small cell lung cancer." (PMID 33377624, 2021). "It has been previously reported that XCR1 mRNA expression in MDA-MB-231 cells is lower than that in the other breast cancer cell lines such as MCF-7 cells." (PMID 33374849, 2020). "The role of XCR1 in breast cancer cells was also investigated using triple-negative MDA-MB-231 human breast cancer cells." (PMID 33374849, 2020). "In breast cancer, overexpressed XCR1 inhibits cell growth and tumorigenesis via suppression of the MAPK and PI3K/AKT/mTOR signaling pathways." (PMID 33374849, 2020). "XCR1 is overexpressed in ovarian carcinoma, oral cancer, and breast cancer." (PMID 33377624, 2021). "The expression of XCR1 is inhibited in human breast cancer cells in vitro and in vivo through inhibiting the mitogen‐activated protein kinase (MAPK) and phosphatidylinositol‐4,5‐bisphosphate 3‐kinase (PI3K)/AKT/mammalian target of rapamycin (mTOR) signaling pathway." (PMID 33377624, 2021). "Besides, the overexpression of XCR1 can promote the growth, migration, and invasion in breast cancer and non-small-cell lung cancer." (PMID 31781309, 2019). "Furthermore, the other three hub genes, IL2RB, XCR1 and CXCR6, have been reported to be related with the prognosis of other cancers, such as early breast cancer, salivary adenoid cystic carcinoma, bladder and hepatocellular cancers." (PMID 33719152, 2021).
melanoma (7 papers, 2013 to 2024). A malignant, usually aggressive tumor composed of atypical, neoplastic melanocytes. "An XCL1 fusion peptide improved tumor rejection in a mouse B16 model of melanoma via recruitment of XCR1+ dendritic cells to the tumor." (PMID 38026637, 2023). "Recently, Shimizu and colleagues showed that vaccination with B16 melanoma cells loaded with the invariant NKT cell ligand αGalCer stimulated tumor-reactive CD8+ memory T cells in a novel mechanism involving cross-talk between XCR1-expressing DC and pDC via NKT-stimulated IFN-α production by pDC." (PMID 24400008, 2013). "We questioned whether the lack of CD11c+/XCR-1+ cDC1 would abolish antigen-specific CD8+ T cell generation and consequent B16F10 clearance of melanoma cells metastatic to the lungs." (PMID 39559560, 2024).
influenza (5 papers, 2015 to 2023). An acute viral infection of the respiratory tract, occurring in isolated cases, in epidemics, or in pandemics; it is caused by serologically different strains of viruses (influenzaviruses) designated A, B, and C, has a 3-day incubation period, and usually lasts for 3 to 10 days. "Influenza M2e was selected as the antigen to be included in VB for targeting pig XCR1, as M2e represents an evolutionary conserved influenza antigen which is promising for generating universal influenza vaccines." (PMID 28794452, 2017). "Altogether we report a promising strategy towards the development of universal influenza vaccine with the finding that M2e-targeting to XCR1 stimulated the anti-M2e IgG response in pigs, and revealed to be more efficient than MPL and CpG TLR ligands." (PMID 28794452, 2017). "Thus altogether M2e-targeting to XCR1 shows promises for a trans-species universal influenza vaccine strategy, possibly avoiding the use of classical adjuvants." (PMID 28794452, 2017). "The strategy could then be rapidly translated to species sensitive to influenza such as human, pigs, horses and even birds which also express XCR1 on cDC68." (PMID 28794452, 2017). "In this study, we showed that targeting the evolutionary conserved M2e influenza antigen to XCR1 using VB platforms promotes anti-M2e antibody responses in pigs, and thus stands as a promising approach towards the development of a universal vaccine against influenza." (PMID 28794452, 2017). "While conferring protection against influenza, targeted delivery of HA to MHC-II molecules, CCR1/3/5, or Xcr1 revealed qualitative differences in induced immune responses." (PMID 26257735, 2015).
non-small cell lung carcinoma (5 papers, 2016 to 2023). A group of at least three distinct histological types of lung cancer, including non-small cell squamous cell carcinoma, adenocarcinoma, and large cell carcinoma. "XCR1 enhances cell growth and migration and is involved in bone metastasis in non-small cell lung cancer." (PMID 27888627, 2016). "Similarly, the prognostic function of XCR1 was displayed in non-small cell lung cancer, hepatocellular carcinoma, and other cancers." (PMID 32500914, 2020). "In previous reports, XCR1 expressed in epithelial ovarian carcinoma (EOC) and non-small-cell lung cancer could promote their proliferation and migration." (PMID 37895310, 2023).
respiratory failure (5 papers, 2021 to 2025). The significant impairment of gas exchange within the lungs resulting in hypoxia, hypercarbia, or both, to the extent that organ tissue perfusion is severely compromised. "Different human polymorphisms have an impact on clinical outcomes: sequence changes in ApoE, TLR7, TMEM189-UBE2V1, as well as SLC6A20, LZTFL1, CCR9, FYCO1, CXCR6, XCR1, have been associated with severe disease outcomes as well as respiratory failure." (PMID 35207458, 2022).
diabetes (4 papers, 2014 to 2024). "Those genes were all previously related to the insulin pathway or diabetes, where XCR1 (encoding a chemokine receptor) even linked obesity to insulin resistance before." (PMID 25071839, 2014). "Deletion of the Xcr1+ NLT DC in the NOD.Batf3−/− mice resulted in absence of presentation of MHC-I epitopes in the pLN and no incidence of diabetes." (PMID 26300591, 2015).